TLR4 (toll like receptor 4)
Diseases named in the same sentence as TLR4 in open-access papers (continued):
Sharing a sentence is not in itself a finding about the gene and the disease.
Obesity (continued). "Obesity alters the gut microbiome and is associated with increased circulating LPS, which initiates adipose tissue inflammation and macrophage activation in a manner dependent on intact TLR4 signaling, a phenomenon coined “metabolic endotoxemia”." (PMID 31497027, 2019). "The loss of gut barrier integrity itself in obesity results in systemic endotoxemia which too contributes to vWAT macrophage activation, possibly through bacterially-derived lipopolysaccharide (LPS) acting on local toll-like receptor 4 (TLR4)." (PMID 31225498, 2019). "Based on prior studies in young male TLR4 KO mice, we hypothesized that TLR4 KO mice would be protected from obesity‐associated inflammation and insulin resistance leading to protection from HFD‐induced knee OA progression." (PMID 31044181, 2019). "In obesity-associated metabolic inflammation, FFAs may act as ligands for TLR4 and thus induce TNF-α production by monocytes/macrophages, which suggests pathological interactions between FFAs and TLR4." (PMID 31443599, 2019). "Collectively, these findings support and extend prior work by Milanski and colleagues that implicated TLR4 in obesity-induced glial activation in hypothalamus, which may contribute to systemic metabolic disturbances." (PMID 30396359, 2018). "It is already known that TLR4-deficient mice develop obesity when fed a HF diet." (PMID 29666152, 2018). "Obesity-associated inflammation is mostly related to TLR4-NF-κB pathway." (PMID 30050954, 2018). "The pattern recognition receptor Toll-like receptor 4 (TLR4) activates signaling pathways that may be particularly important in mediating obesity-associated microglial activation and its consequences." (PMID 30396359, 2018). "Clinical as well as preclinical experimental studies show that Toll-like receptor 4 (TLR4) expression and activation is directly associated with obesity-induced tissue inflammation; abrogation of TLR4 is able to reverse insulin resistance and pancreatic β-cell dysfunction in experimental models." (PMID 29426925, 2018). "In mixed BM chimeras, the TLR4-sufficient donor partner exhibits obesity-driven BM lympho-myeloid alterations, whereas the TLR4-deficient donor partner is protected, demonstrating a mechanistic contribution of BM cell-autonomous TLR4 activity." (PMID 29453396, 2018). "Thus, we define ARC-restricted TLR4 knockdown as a potential strategy to combat metabolic disorders associated with obesity." (PMID 28785099, 2017). "Saturated fatty acids can activate TLR4, and TLR4‐deficient mice were protected from high fat diet (HFD)‐induced obesity and insulin resistance, suggesting that TLR4‐mediated inflammation may cause metabolic dysfunction, such as obesity and insulin resistance." (PMID 28776958, 2017). "TLR4 activation has been well-linked to the etiology of insulin resistance in obesity, contributing to meta-flammation most often via ligation by palmitic acid, levels of which are increased in obesity." (PMID 27812198, 2016). "Obesity is characterized with increased expression of genes involved in lipid metabolism and inflammation, so we also examined several obesity-associated genes, including TLR-4, GPR40 and 43, Fabp1, Scd1, and Mttp." (PMID 27599699, 2016). "Furthermore, mice deficient in TLR-4 are not only protected from LPS-induced obesity and NAFLD, but also from high-fat diet-induced obesity and NAFLD, as well as NAFLD and NASH in different rodent models." (PMID 27043550, 2016). "Besides involving in the classical TLR4-MyD88-dependent signaling pathway related to atheroscleorsis, MyD88 has been also played an important role in obesity-associated inflammatory diseases, including insulin resistance and atherosclerosis." (PMID 26959040, 2016). "Besides bacterial danger signals mediated by lipopolysaccharide (LPS), the toll-like receptor 4 (TLR4) ligand, obesity-associated metabolic danger signals also play an important role in macrophage polarization." (PMID 28018292, 2016).
Obesity (continued). "We addressed the question whether obesity-associated hypertension is reduced in TLR4 SNP rs4986790 cases." (PMID 26435700, 2015). "We hypothesized that TLR4 ligands are involved in obesity-associated hypertension and investigated the TLR4 single nucleotide polymorphism (SNP rs 498790)." (PMID 26435700, 2015). "Finally, our data suggest that inactivation of aberrant TLR4 function offer a novel therapeutic strategy to prevent and/or treat obesity-induced cardiac insulin resistance and its associated cardiovascular co-morbidities." (PMID 26539824, 2015). "Finally, loss of function of the LPS receptor Toll-like receptor 4 (TLR4) or of its co-receptor CD14 prevents insulin resistance during diet-induced obesity or induced by fatty-acids." (PMID 25383781, 2014). "Moreover, experiments in mice with a mutation in the receptor TLR4 seem to protect these mice against the development of diet-induced obesity." (PMID 24835211, 2014). "Moreover, free fatty acids serve as ligands for the toll-like receptor 4 (TLR4) complex and stimulate cytokine production of macrophages, thereby modulating inflammation of adipose tissue which contributes to obesity-associated metabolic complications." (PMID 24733068, 2014). "Further, studies on adipose tissue using mouse models with selective post-receptor, loss-of function mutations in TLR4 have demonstrated that TLR4 deficiency is protective against the deleterious inflammatory effects associated with obesity and metabolic disease." (PMID 25101057, 2014). "Indeed numerous studies consistently demonstrate that TLR4 deficiency protects against the development of diet-induced obesity and insulin resistance." (PMID 24594974, 2014). "Likewise, mice with loss-of-function mutation in TLR4 are protected against the development of diet-induced obesity and insulin resistance." (PMID 22509382, 2012). "Finally, the role of TLR4 (the endotoxin signaling receptor) is further suggested by studies demonstrating reduced diet induced obesity and atherosclerosis in TLR4 deficient mouse models." (PMID 22709547, 2012). "Indeed, TLR4 is directly implicated in diet induced obesity and atherosclerosis through studies in TLR4 deficient mouse models." (PMID 22709547, 2012). "Otherwise, obesity-associated endocrine disorders in adipocytes can activate monocytes and subsequently trigger atherosclerosis, and adiponectin can inhibit this process through decreasing TLR4 expression on macrophage/monocytes." (PMID 21226932, 2011). "We investigated whether mice with loss of function mutation in TLR4 were resistant to TF-induced pathologies such as obesity, inflammation, hyperglycemia, and hyperinsulinemia." (PMID 21314942, 2011). "TLR4 deficient/mutated mice have been shown to protect from obesity-associated insulin resistance." (PMID 20824098, 2010). "This study clearly demonstrates that the LPS induced activation pathway is an integral part of the inflammatory process linked to obesity, and that adipocytes are responsible for most of the secreted TNFalpha in inflamed adipose tissue, through TLR4 activation." (PMID 20148136, 2010). "However, whether irisin directly modulates obesity-associated hypothalamic inflammation, particularly through TLR4-dependent pathways, remains unknown." (PMID 41748769, 2026). "Polymorphisms within the coding or promoter regions of the TLR4 gene can modify the receptor’s responsiveness to lipopolysaccharides (LPS), enhancing immune and inflammatory signaling and thereby contributing to the development of obesity and related metabolic disorders." (PMID 41226745, 2025). "However, it remains unclear whether TRAF3 and TLR4 signaling is associated with siglec-E that alters AT microenvironment to mediate obesity and AT inflammation." (PMID 39967660, 2025).
Obesity (continued). "Both studies highlight the role of intervention measures in reducing inflammation, demonstrating that modulation of the TLR-4/NF-κB and other related signaling pathways can play a crucial anti-inflammatory and protective role in metabolic disorders associated with diabetes or obesity." (PMID 39759101, 2024). "Another modality to prevent or possibly treat obesity and glaucoma is to intervene directly with drugs capable of reducing inflammation or regulating proteins/genes that are key components of the proinflammatory mechanisms underlying the two pathologies, such as TLR4." (PMID 36674680, 2023). "TLR4 is an important binding regulator of LPS, which is overexpressed in intestinal mucosal epithelial cells after stimulation of activation, inducing the production of various pro-inflammatory factors and causing and maintaining obesity-type low-level inflammation in the body." (PMID 36936157, 2023). "Phytochemicals that inhibit the activation of TLR4, may ameliorate obesity associated symptoms." (PMID 35769384, 2022). "Furthermore, obesity promotes the initiation of numerous pro-inflammatory pathways by causing TLR4-mediated inflammatory responses that involve activation of the transcription factor NF-κB and the production of pro-inflammatory mediators such as IL-6, IL-1, and TNF-α." (PMID 35740977, 2022). "When it comes to increased leakage of LPS and fatty acids and overloading of lipid, TLR4 and ER stress may be triggered to activate systemic inflammation via cross-interaction, which leads to obesity-associated insulin resistance and oxidative stress (OS) (34, –, 36)." (PMID 35583337, 2022). "Furthermore, experimental studies have revealed that disruption of the TLR4 gene could protect against the inflammation and insulin resistance caused by obesity." (PMID 32708841, 2020). "Tissue specific TLR4 effects have been studied in the past and confirmed observation from global deletions, e.g. myeloid-specific (as well as global) TLR4-deficiency improves insulin sensitivity and inhibits obesity-induced tissue inflammation in HFD and lipid infusion models." (PMID 29426925, 2018). "TLR4 gene deletion in mice has a protective effect against adipose tissue inflammation and against the resistance to insulin action that is induced by the intake of a high fat diet, a fact that points towards the causal role played by TLR4 in metabolic changes driven by over-eating and obesity." (PMID 29601492, 2018). "However, whether the effect of oral resveratrol on obesity-related OA was associated with TLR4 signaling pathway is still obscure." (PMID 28250578, 2017). "Recently, TLR4 signaling was shown to play a direct role in mediating adipose tissue macrophage phenotype in diet-induced obesity and may shed some light on why TLR4 deficiency results in decreased adipose tissue inflammation despite that the prevalence of ATMs is not reliably reduced." (PMID 24594974, 2014). "Taking into account the role of TLR4 as a molecular gate linking inflammation with insulin resistance, diabetes, and obesity and that genetic associations may vary largely with environmental factors, we propose to study if the smoking habit influences the effect of genetic variation." (PMID 23239997, 2012). "Indeed, while some reports described noeffect on body weight, other authors described an increased bodyweight or, in contrast, a protection against diet-induced obesity.Similarly, adiposity and food intake were either reported to be unchanged,increased, or decreased in TLR4-deficient animals." (PMID 18350123, 2008). "This review aims to summarize recent research on the pathobiological roles of TLR4-mediated inflammation in obesity and its contribution to the development of metabolic disorders." (PMID 41698753, 2026). "TLR4 is a type I transmembrane protein that plays a critical role in innate immunity by recognizing LPS and FFAs both elevated in obesity and MASLD." (PMID 41598496, 2026).
Obesity (continued). "Recent studies have highlighted the central role of TLRs, particularly TLR4, in the development of obesity-related metabolic disturbances." (PMID 41598496, 2026). "The increased expression of TLR4 observed in obesity is believed to contribute to the development of type 2 diabetes (T2D), as it disrupts key physiological processes that regulate metabolic inflammation." (PMID 41698753, 2026). "Multiple studies have indicated that TLR4 regulates inflammation, adipogenesis, thermogenesis, and glucose metabolism through its interaction with endotoxins, particularly in the context of obesity." (PMID 41698753, 2026). "A positive correlation has also been found between TLR4 expression and body mass index (BMI) in patients with obesity or T2DM." (PMID 40076851, 2025). "In the metabolic obesity of mice, failure of TLR4 protects against insulin resistance and diet-induced obesity (DIO)." (PMID 40076851, 2025). "Experimental evidence shows that obesity triggers vascular inflammation via lipid-induced activation of TLR4/NF-κB signaling, whereas insulin resistance enhances mitochondrial ROS production." (PMID 41393256, 2025). "As FFAs can bind to inflammatory receptors such as TLR4 that drive cytokine production, it is possible that Jak2/Stat3 mediates FA binding to TLR4 to potentiate adipose tissue inflammation during obesity." (PMID 40801626, 2025). "Saturated fatty acids, released in large quantities from hypertrophied adipocytes via macrophage-induced adipocyte lipolysis, contribute to the obesity-induced inflammatory state in the vascular wall by triggering the TLR4/NF-κB pathway." (PMID 39198360, 2025). "Other ligands for TLR4 likely contribute to persistent reprogramming of myeloid cells, as shown by unsaturated fatty acid in diet-induced obesity." (PMID 40795290, 2025). "Mice with hepatocyte-specific KO of TLR4 (Tlr4LKO) fed a high-fat diet to induce obesity had improved glucose tolerance and insulin sensitivity compared with control mice." (PMID 40985048, 2025). "Microbial lipopolysaccharides are the main agonists of TLR4, but saturated fatty acids and fibrinogen have been suggested as stimuli for TLR4 dimerization and signaling cascade activation in the context of obesity." (PMID 40723425, 2025). "TLR4 and its impact on inflammation and obesity have been previously studied, and some have examined the impact of WD on TLR4." (PMID 40637163, 2025). "Newly discovered H3K4me3 enrichments at the TLR4 promoter and E2F targets highlight epigenetic imprinting by diet-induced obesity within HSPCs." (PMID 40795290, 2025). "Some metabolic complications, such as insulin resistance and β-cell dysfunction, are related to the overexpression of TLR2 and TLR4 in patients with obesity and DM." (PMID 40076851, 2025). "TLR4 can bind to other molecules, such as resistin, a cytokine that has shown a role in the physiology of obesity and DM." (PMID 40076851, 2025). "In this study, we have characterized, for the first time, the impact of TLR4 signaling on small intestine ENS morpho-functional integrity in a mouse model of 8-week HFD-induced obesity." (PMID 41226745, 2025). "A study on the relationship between obesity and arthritis revealed that saturated fatty acids activate TLR4, which initiates the recruitment of MyD88." (PMID 40636390, 2025). "As shown in this study, IBC patients with obesity and highly proliferative tumors had increased percentages of TLR4 and AGER." (PMID 40647480, 2025). "Several investigations on HFD-induced obesity revealed that HFD causes impaired GI transit, increased plasma LPS concentrations, and TLR4-mediated release of pro-inflammatory cytokines and myenteric neuron apoptosis primarily in the colon." (PMID 41226745, 2025). "These authors propose a model in which pro-inflammatory monocytes in individuals with obesity respond to circulating factors via Toll-like receptors (TLR4 and TLR8)." (PMID 39861442, 2025).
Obesity (continued). "Catechins reduced body mass, adiposity, and inflammation in an induced obesity model via increased adiponectin expression and reduced TLR4/TNF‐α signaling." (PMID 40195898, 2025). "Obesity also activates the lipopolysaccharide/toll-like receptor 4 (LPS/TLR4) inflammatory pathway, leading to intestinal microbiota dysbiosis and increased intestinal barrier permeability." (PMID 41150739, 2025). "Overall, our findings highlight a key role for TLR4 signaling in modulating small intestine inflammation and ENS remodeling associated with obesity." (PMID 41226745, 2025). "The TLR4 signaling pathway is recognized as a primary initiator of the inflammatory response induced by obesity." (PMID 39201554, 2024). "This connection between metabolic status and immune activation further complicates the inflammatory milieu in OA, especially of TLR4 in obesity-induced OA, suggesting that metabolic deregulation intensifies DCs-mediated inflammation in OA." (PMID 39596150, 2024). "In obesity, free fatty acids released from adipocytes bind to toll-like receptor 4 (TLR4), promoting proinflammatory cytokine TNF-α, and induce chronic inflammation." (PMID 38396804, 2024). "Increased LPS concentrations in the intestines of obesity-prone rats coincided with the increase in TLR4 expression." (PMID 39201665, 2024). "After exposure to PM2.5 for twelve weeks, the mice developed increased toll-like receptor 4 (TLR4) and Ikbke (related to NF-kB) expression, leptin and insulin resistance, and a worsening of their energy homeostasis and development of frank obesity." (PMID 38665261, 2024). "This mini-review focuses on the potential impact of PM2.5 exposure on the TLR4 signaling pathway, its contribution to leptin resistance, and dysbiosis that exacerbates the link between obesity and AD." (PMID 38933275, 2024). "The established models in this study would help to screen suitable TLR4 inhibitors for application in curing obesity and diabetes." (PMID 38275739, 2024). "Obesity-induced inflammation is mainly activated by the TLR4 signaling pathway, which in turn activates the downstream pathway nuclear factor kappa B (NF-κB) and causes the production of pro-inflammatory factor TNF-α, further aggravating the inflammation." (PMID 38275739, 2024). "Current findings indicated that there existed a disparity in the Bacteroidetes-to-Lactobacillus ratio among individuals with obesity, accompanied by decreased methylation levels of TLR4 and TLR2 genes." (PMID 39733798, 2024). "A slightly higher obesity rate was found in female TLR4-/- mice compared to female WT mice in this study, but nearly no female diabetic mice were obtained in the TLR4 deficiency groups." (PMID 38275739, 2024). "Toll-like receptor 4 (TLR4) detects LPS, activating proinflammatory signaling pathways that induce insulin resistance and exacerbate obesity." (PMID 38792681, 2024). "On the other hand, increasing the level of TLR4 has led to an increase in intestinal permeability and acceleration of obesity." (PMID 38626052, 2024). "This study investigated the change in body weight, blood glucose, and blood lipids in both male and female wild-type (WT) and TLR4 gene knockout (TLR4−/−) mice during the development of obesity or diabetes models." (PMID 38275739, 2024). "The observed suppression of the MD-2/TLR4/NF-κB pathway highlights ISL’s therapeutic potential for obesity-related renal disorders." (PMID 39765652, 2024). "Studies have demonstrated that blocking TLR4 can improve the insulin-dependent intake of glucose, alleviating insulin resistance induced by obesity in mice." (PMID 38275739, 2024). "Adipocytes express the required receptor for bacterial LPS, TLR4, at increased levels in the context of obesity." (PMID 39421246, 2024). "This study should provide new insights into the role of TLR4, as well as opportunities to target novel approaches to the prevention and treatment of metabolic diseases like obesity and diabetes." (PMID 38275739, 2024).